C16orf87 (chromosome 16 open reading frame 87)
Tractability: No criterion of Open Targets' tractability assessment is met for any kind of drug.
Gene: Protein-coding gene on chromosome 16 (46,796,603 to 46,831,180, reverse strand). Ensembl gene ENSG00000155330.
Subcellular location (Human Protein Atlas): Nucleoplasm; Nuclear bodies
Gene Ontology:
Molecular function: protein binding
Genetic constraint (gnomAD): Loss-of-function variants: 3 observed, 5.08 expected, observed/expected ratio (o/e) 0.59, 90% interval 0.27 to 1.48. That is too few expected variants to judge how well the gene tolerates losing a copy. Missense variants: 35 observed, 45.76 expected, observed/expected ratio (o/e) 0.76, 90% interval 0.58 to 1.01. Synonymous variants: 15 observed, 15.35 expected, observed/expected ratio (o/e) 0.98, 90% interval 0.65 to 1.5.
Homologues: Orthologues: chimpanzee C16H16orf87 (100% identical), macaque C20H16orf87 (100% identical), rabbit C16orf87 (100% identical), mouse 4921524J17Rik (99% identical), rat C19h16orf87 (99% identical), dog C16orf87 (98% identical), guinea pig C16orf87 (98% identical), pig C16orf87 (97% identical), tropical clawed frog c4h16orf87 (73% identical), zebrafish C7H16orf87 (60% identical).
Diseases named in the same sentence as C16orf87 in open-access papers:
C16orf87 is named in the same sentence as 3 diseases in open-access papers, as found by Europe PMC text mining. Sharing a sentence is not in itself a finding about the gene and the disease. The quoted sentences say what the papers report.
tumor (1 paper, 2022). "Six genes overlapped in the three top 50 lists for tumor response, overall clinical response, and PFS, including MAGOH, C16orf87, ORC1, NAA35, PWP2, and SIAH2." (PMID 35892846, 2022).
C16orf87 also shares sentences with these, for which no sentence is quoted: cancer (1 paper); thymoma (1).